DES (desmin)
Diseases named in the same sentence as DES in open-access papers (continued):
Sharing a sentence is not in itself a finding about the gene and the disease.
cardiomyopathy (continued). "It is important to note that although protein aggregates are the hallmark of desmin-related cardiomyopathy, their accumulation is only weakly correlated with disease severity, while the amount of pre-amyloid oligomers more strongly correlates with human cardiovascular disease." (PMID 38474073, 2024). "Clinical and experimental investigations have reported that mutations in the DES gene, such as p.A120D, a desmin variant, cause defective formation of intermediate filaments in ventricular cardiomyocytes, leading to the development of arrhythmias or cardiomyopathies." (PMID 36983924, 2023). "Thus, the detailed delineation of exact mechanisms of autophagy impairment in various desmin mutations can help the precise targeting of molecular pathogenesis of desmin-related myopathies and cardiomyopathies." (PMID 37277577, 2023). "However, while desmin-related myopathies and cardiomyopathies are mostly caused by filament formation defects, in plectinopathies, desmin aggregation is a consequence of missing linkages between the IFs and other structures, such as the Z-disks." (PMID 37174658, 2023). "Cardiomyopathies associated with desmin abnormalities are well known." (PMID 35625721, 2022). "Desmin mutations cause familial and sporadic cardiomyopathies." (PMID 36233322, 2022). "Furthermore, a known pathogenic lamin A/C variations can lead to desmin dysfunction as was shown in a cardiomyopathy LmnaH222P/H222P mouse model." (PMID 36158202, 2022). "Cytoskeletal protein variants include variants in desmin, lamin A/C, titin, myosin heavy and light chain, junctophilin, nucleoporin, nesprin, and filamin C. These cytoskeletal protein variants have a strong association with the development of cardiomyopathy." (PMID 35159226, 2022). "In the future, new identified cardiomyopathies related genetic variants (i.e., novel desmin (DES) indel mutation) could represent additional research targets also in the Cardio-Oncology field." (PMID 35413811, 2022). "On the other hand, in the desmin deficient mice, while overexpressed osteopontin induced secretion of profibrotic galectin-3 by infiltrating macrophages and promoted cardiomyopathy, inhibition of osteopontin or complement components C5a (CD88) and C5ar improved the disease." (PMID 33923914, 2021). "This mutation is located within a region which is involved in the coiled coil formation of desmin dimers, and leads to abnormal cytoplasmic aggregation of desmin suggesting that this region may be a hotspot of cardiomyopathy-related mutations." (PMID 33429969, 2021). "Dominant or recessively inherited missense mutations or in-frame deletions in desmin lead to a range of phenotypic syndromes that can include distal myopathy, limb girdle weakness, congenital weakness, and cardiomyopathy, yet all are unified by desmin aggregation within the affected tissue." (PMID 31371504, 2019). "One striking example of an aggregate-associated cardiomyopathy is the desmin-related form." (PMID 31361162, 2019). "However, the protein has also been implicated in skeletal muscle disease (myofibrillar myopathy,) and desmin-related cardiomyopathy, e.g. caused by the R120G mutation in CRYAB." (PMID 30048712, 2018). "Desmin is part of a large multigene family of IF cytoskeletal proteins responsible for the mechanical and stress-coping resilience of cells and no more so than in muscle where the targeted deletion of desmin from the mouse genome causes cardiomyopathy, fibrosis and heart failure." (PMID 28470624, 2017). "Hence, it was concluded that the mitochondrial abnormalities, which are regarded as the primary cause of the cardiomyopathy in desmin knockout mice, can be ameliorated by the overexpression of Bcl-2." (PMID 23143191, 2013). "Here, we inquired whether desmin acts as a modifier in DMD‐associated cardiomyopathy." (PMID 41163301, 2025). "Also, dominant mutations in desmin are associated with a severe form of cardiomyopathy." (PMID 35741135, 2022).
cardiomyopathy (continued). "We also investigated a potential impact of hUSP5 overexpression on the increased autophagic flux in desmin-related cardiomyopathies." (PMID 39841822, 2025). "Across multiple mouse models of desmin-related cardiomyopathies, MLF2 was consistently enriched in protein aggregates and interacted with key proteins involved in protein quality control, including αB-crystallin (CryAB)." (PMID 41590846, 2025). "Although the precise role of desmin in cardiomyopathy progression remains only partially understood, our results position this protein as a key structural player in the context of DMD." (PMID 41163301, 2025). "Given the early-onset nature of desmin-related cardiomyopathy, which often manifests in the second or third decade of life, her lack of clinical signs suggests either a lack of variant expression in cardiac tissue or reduced disease penetrance." (PMID 40606663, 2025). "Cytoplasmic aggregates are seen in desmin-related cardiomyopathies (DRM), caused by genetic mutations affecting desmin or its chaperone αB-crystallin." (PMID 40658643, 2025). "Mutations in desmin or CRYAB lead to common molecular defects known as desminopathies that involve impaired mitochondrial morphology leading to cardiomyopathies, as a result of desmin aggregation or reduction in desmin and CRYAB29–31." (PMID 40480980, 2025). "It was found that doxycycline can prevent aberrant protein aggregation in mice with CRYABR120G desmin-related cardiomyopathy, but interestingly, it does so through an autophagy-independent mechanism as opposed to the previously discussed therapeutics." (PMID 38474073, 2024). "In summary, this work highlights the deleterious effects of DESE439K mutation and crucial role of mitochondrial abnormalities in the pathophysiology of desmin-related cardiomyopathy." (PMID 38167524, 2024). "Both residues are related to cardiomyopathies in humans, and Ser32 is also a phosphorylation site, which contributes to desmin assembly and cardiac toxic PAOs deposition." (PMID 38607042, 2024). "Consequently, desmin mutations alter the mechanical properties of the desmin network, resulting in multiple functional and structural abnormalities in muscle cells, leading to progressive skeletal myopathy and cardiomyopathy, the most common clinical manifestations of MFM1." (PMID 38167524, 2024). "This work highlights the deleterious effects of DESE439K mutation, demonstrates the crucial role of mitochondrial abnormalities in the pathophysiology of desmin-related cardiomyopathy, and opens up new potential therapeutic perspectives for this disease." (PMID 38167524, 2024). "Further emphasizing the role of Ankrd1 in cardiac diseases, its expression is also upregulated in desmin-related cardiomyopathy, where Ankrd1 interacts with the type III intermediate filament desmin." (PMID 39420247, 2024). "Mutations in the DES gene are associated with various muscular and cardiac pathologies, so-called desmin-related myopathies or cardiomyopathies." (PMID 37277577, 2023). "As evidence, overexpression of the SUMO E2 conjugating enzyme Ubc9 reduces pathogenic protein aggregation and improves cardiac function in a desmin-related cardiomyopathy model." (PMID 38201212, 2023). "Autosomal dominant or recessive mutations in the desmin gene (DES) result in a variety of diseases, including cardiomyopathies and myofibrillar myopathy, collectively called desminopathies." (PMID 37446359, 2023). "Cardiomyocyte death also accompanies virtually all forms of inherited cardiomyopathies, including Duchenne muscular dystrophy, Danon and desmin cardiomyopathies." (PMID 37839355, 2023). "Mutations affecting both lamin and desmin (type V and type III intermediate filament proteins, respectively), commonly give rise to conditions associated with cardiomyopathy and heart failure." (PMID 37498175, 2023). "Conversely, in vivo overexpression ATG7 in mice improves autophagic capacity that ameliorates desmin-related cardiomyopathy." (PMID 36939901, 2023).
cardiomyopathy (continued). "In a cardiomyopathy LmnaH222P/H222P mouse model, desmin organization was disrupted and accumulated in the cytoplasm." (PMID 35159226, 2022). "This was important to draw a correlation between these biomarkers and the pathogenesis of DM-induced desmin and sarcomere damage and cardiomyopathy." (PMID 35625721, 2022). "The critical role of desmin in cardiac function is demonstrated by its implication in various cardiomyopathies as well as in cardiac conduction-related pathologies." (PMID 35625721, 2022). "One previous study showed that the non-toxic HSP inducer geranylgeranylacetone (GGA), a nontoxic antiulcer drug and inducer of small HSPs can inhibit desmin-related cardiomyopathy progression." (PMID 36158202, 2022). "Nicorandil, a vasodilatory drug, was shown to prevent ventricular tachyarrhythmias induction by normalizing Cx43 expression in this desmin-related cardiomyopathy mouse model." (PMID 36158202, 2022). "As the role of desmin in cardiomyopathies has been discussed thoroughly, the current review is focused on the role of desmin impairment as a trigger for cardiac arrhythmias." (PMID 36158202, 2022). "One of the critical steps for a future therapeutic approach to desmin cardiomyopathies is to characterize representative animal models (e.g., mice, zebrafish) that phenocopy desmin aggregation in patients." (PMID 36158202, 2022). "Our observation is also in concordance with previous observations in a desmin and αB‐crystallin cardiomyopathy mouse model where increased cardiomyocyte p62 was demonstrated." (PMID 33605084, 2021). "In this study, using an NGS approach, we identified the desmin mutation DES-c.735G>C in an index patient from a family, in which several members developed skeletal myopathies or cardiomyopathies." (PMID 34680517, 2021). "The immunohistochemical reaction to desmin lets the authors note that myocardial cells contain varying amounts of desmin in cobalt cardiomyopathy." (PMID 33546142, 2021). "Consistent with a major pathogenetic role of mitochondrial dysfunction, overexpression of Bcl-2 corrects mitochondrial defects and ameliorates inherited desmin null cardiomyopathy." (PMID 33923914, 2021). "As a major IF in the functional interaction of mitochondria and the cytoskeleton, desmin is crucial in physical and pathological processes that lead to cardiomyopathy and heart failure." (PMID 34285704, 2021). "While initially identified in desmin-related genetic cardiomyopathies, these features of desmin mis-localization, as well as sarcomeric disarray, are increasingly identified as features of cardiomyopathy in general." (PMID 32581848, 2020). "These collapses in desmin networks contribute to altered mitochondrial position and distribution, resulting in dysfunctional cardiac proteostasis and the development of cardiomyopathy." (PMID 32982788, 2020). "In a mouse model with desmin-related cardiomyopathy a remodelling of gap junction proteins such as Cx43 was observed, which is in accordance with the findings of the present study." (PMID 32584885, 2020). "It is furthermore related to heart diseases, including cardiomyopathies, and found to interact with desmin, which is related to cardiomyopathies." (PMID 32411128, 2020). "Analogously, we have demonstrated that TFEB-induced upregulation of HspB8, a BAG3 partner, was essential for chaperoning desmin back to its physiologic localization state in a mouse model of R120G αB-crystallin induced cardiomyopathy." (PMID 32581848, 2020). "The pivotal role of the desmin IF cytoskeletal network is underscored by the fact that over 120 mutations of the human DES gene cause hereditary and sporadic myopathies and cardiomyopathies." (PMID 33192292, 2020). "Other cytoskeletal protein aggregates have been described in cardiomyopathies: in desmin-related cardiomyopathy, desmin, an intermediate filament, forms aggregates in cardiomyocytes." (PMID 31847412, 2019).
cardiomyopathy (continued). "Mice expressing the mutant CryABR120G, a proteotoxic model of desmin-related cardiomyopathy, are characterized by increased accumulation of misfolded protein aggregates in the hearts." (PMID 29576856, 2018). "Similar to desmin-related cardiomyopathy, the Myozap-overexpressing hearts showed increased protein aggregate formation." (PMID 29576856, 2018). "BD cytoplasmic inclusion bodies of heart muscle cells in the majority of elderly individuals are different from other cardiomyopathies including those with inclusions containing mutant proteins such as desmin or valosin-containing protein." (PMID 30413735, 2018). "Although the exact components of PAOs in the heart are still not clear, desmin aggregates have been reported to be the major PAO element in desmin-related cardiomyopathy." (PMID 29088822, 2017). "The term “desminopathies” stands for a group of familial and sporadic myopathies and cardiomyopathies that are caused by mutations in the human desmin (DES) gene on chromosome 2q35, which encodes the muscle-specific intermediate filament protein desmin." (PMID 27393313, 2016). "Desmin-positive protein aggregates as well as granulofilamentous and electron-dense amorphous materials are also the morphological hallmarks of desmin cardiomyopathies." (PMID 23143191, 2013). "Herein, desmin-related cardiomyopathy represents a conformational disease that is attributed to improper folding of the desmin protein." (PMID 23508734, 2013). "Protein misfolding and UPS dysfunction also appears to play a role in desmin-related cardiomyopathies, which result in congestive heart failure." (PMID 21808733, 2011). "Indeed the analysis of the effects of the cardiomyopathy causing mutant R120G αB-crystallin adds to this argument as this residue is outside of the β8-strand studied here, but is part of the β7-strand identified from the pin-arrays to be involved also in binding to desmin." (PMID 22096479, 2011). "In the present study, we analyzed the effect of nicorandil, a mitoK(ATP) channel opener, on disease progression such as mitochondrial injury and the occurrence of apoptotic cell death concomitant reduction in survival rate in the desmin-related cardiomyopathy." (PMID 21541347, 2011). "Finally, we deleted or reduced desmin in mdx mice and observed a worsening of the dystrophic phenotype, including the development of cardiomyopathy." (PMID 41163301, 2025). "The essential role of desmin in human skeletal muscle is highlighted by the observation that mutations in the human desmin gene (DES) cause autosomal‐dominant, autosomal‐recessive and sporadic myopathies and cardiomyopathies." (PMID 41165044, 2025). "Pathogenic variants in other cytoplasmic intermediate filaments like desmin (DES) cause cardiomyopathies, for example, non-compaction cardiomyopathy." (PMID 39940784, 2025). "Transgenic expression of P209L BAG3 in the mouse heart induced protein aggregates, with sequestration of endogenous WT BAG3 as well as sarcomere-associated proteins such as desmin, α-actinin, and myopodin (SYNPO-2) in aggregates, provoking sarcomere disruption and cardiomyopathy." (PMID 39932799, 2025). "In addition, other cytoskeleton elements are also involved in the attachment of mitochondria to sarcomeres, such as desmin, the muscle-specific intermediate filament protein that was previously studied in cardiomyopathy research." (PMID 40149568, 2025). "Furthermore, overexpression of PA28 (a proteasome activator) in cardiomyocytes prevents desmin-related cardiomyopathy and myocardial I/R injury." (PMID 39516219, 2024). "Finally, we challenged the impact of mitochondrial abnormalities as a main mechanism in the emergence of desmin-related cardiomyopathy in DESE439K patients by implementing a treatment with extracellular vesicles (EVs) containing healthy mitochondria." (PMID 38167524, 2024).
cardiomyopathy (continued). "ACM-causing mutations have also been identified in genes outside the desmosome, including phospholamban (PLN), filamin C (FLNC), desmin (DES), titin (TTN), and lamin A/C (LMNA), which are linked with other cardiomyopathies, including DCM and neuromuscular cardiomyopathies." (PMID 38610600, 2024). "In a meta-analysis performed in 2011, desmin mutation or lack of desmin function was found to be associated with increased cardiomyopathy, cardiac conduction disease or arrhythmia and atrioventricular blockage (AVB)." (PMID 37108147, 2023). "Additional cluster 3 proteins categorized to cardiomyopathy and sarcomeric proteins exposed to constant mechanical stress, including Desmin (DES), dystrophin muscular dystrophy (DMD); myosin binding protein C, cardiac (MYBPC3); myosin light polypeptide 2 (MYL2); Titin (TTN) and phospholamban (PLN)." (PMID 36681760, 2023). "These mitochondrial changes are at least partly mirrored in our desmin knock-out animals, thus indicating that dysfunctional mitochondria are a common feature in cardiomyopathies irrespective of the underlying aetiology." (PMID 36233322, 2022). "Mutations in the human desmin gene (DES) may cause both autosomal dominant and recessive cardiomyopathies leading to heart failure, arrhythmias and atrio-ventricular blocks, or progressive myopathies." (PMID 36555543, 2022). "In support of this, age‐related cardiomyopathy is recapitulated in adult mice by cardiac‐specific Atg5 deletion and mTORC1 activation, whereas desmin‐related cardiomyopathy, characterized by the accumulation of cytotoxic misfolded proteins, is prevented by cardiac‐selective Atg7 overexpression." (PMID 34554626, 2021). "Indeed, HSP activation has been shown to have beneficial effects on heart function in a mouse model of desmin-related cardiomyopathy in which HSP expression was induced by geranylgeranylacetone." (PMID 33732734, 2021). "Similar to plectin-null, MCK-Cre/cKO, P1-, P1b-, and P1d-KO mice, muscle specimens from these patients showed myofibrillar degeneration, disruption of the desmin networks with formation of desmin aggregates, clustering of nuclei, mitochondrial abnormalities, and symptoms of cardiomyopathy." (PMID 34572100, 2021). "Thus, cardiomyocytes adjacent to fibrotic scars are under multiple stresses, which go along with increased ER/SR stress and the induction of autophagy, a phenomenon also reported in desmin-related cardiomyopathies." (PMID 35011658, 2021). "The highest amounts of aggregates were observed in desmin and phospholamban cardiomyopathy hearts." (PMID 33605084, 2021). "In a similar way, in muscular tissues, by causing significant structural changes as indicated in this study, this mutation probably affects the interaction of human αB-crystallin with its significant target protein (desmin), providing the basis for development of the cardiomyopathy." (PMID 34843556, 2021). "Mutations in desmin cause desmin-related myopathy (OMIM#601419) and cardiomyopathy (OMIM#604765)." (PMID 34768808, 2021). "Both a strategy of overexpressing αB-crystallin that resulted in chaperoning desmin to its physiologic location, or inducing haplo-insufficiency of desmin rescued cardiomyopathy by preventing desmin-induced sequestration of sarcomeric proteins from their physiologic location." (PMID 32581848, 2020). "Activation of the autophagy-lysosome pathway by intermittent fasting or targeted activation of transcription factor EB even at an advanced stage of disease pathogenesis was sufficient to restore normal function and rescue cardiomyopathy by restoring normal desmin localization." (PMID 32581848, 2020). "Besides the hub genes of MYBPC3, MYH7, and DSP, these subnetworks also include several genes that have been implicated in cardiomyopathy, such as TPM1, ACTC1, DES, TCAP, JUP, and DSG2." (PMID 32344918, 2020).